HOXB7 (homeobox B7)
Diseases named in the same sentence as HOXB7 in open-access papers (continued):
Sharing a sentence is not in itself a finding about the gene and the disease.
hepatocellular carcinoma (7 papers, 2013 to 2025). A malignant tumor that arises from hepatocytes. "Recently, upregulated HOXB7 has been demonstrated to be a significant independent risk factor for hepatocellular carcinoma recurrence and survival after curative resection." (PMID 30664713, 2019). "Homeobox B7 (HOXB7) has been identified associated with poor prognosis of hepatocellular carcinoma (HCC)." (PMID 28646927, 2017). "A similar study showed that HOXB7 was highly expressed in hepatocellular carcinoma, where it promoted cell proliferation, upregulated cancer stem cell markers EPCAM and NANOG, enhanced c-Myc and Slug expression, and promoted tumor growth." (PMID 41040515, 2025). "Bioluminescence imaging was used to survey the effect of HOXB7 on the metastatic ability of hepatoma cells in vivo." (PMID 28646927, 2017). "In line with previous reports, our results showed that HOXB7 facilitated hepatoma cells proliferation." (PMID 28646927, 2017). "A recent study has also reported that HOXB7 accelerated hepatoma cells proliferation and metastasis by activating the MAPK/ERK pathway." (PMID 28646927, 2017). "The expression level of HOXB7 in different human hepatoma cell lines was detected, and SMMC-7721 cells exhibited higher expression level of HOXB7, while the expression in HepG2 was lower." (PMID 28646927, 2017). "After verifying the association between HOXB7 and HCC prognosis, we next sought to identify the biological function of HOXB7 in hepatoma cell growth." (PMID 28646927, 2017). "Quantification of luciferase activity showed that HOXB7 conferred stronger metastasis ability on hepatoma cells (P < 0.01)." (PMID 28646927, 2017). "Survival analysis revealed that HOXB7 knockdown in hepatoma cells contributed to a longer survival time and up-regulation of HOXB7 led to a worse outcome." (PMID 28646927, 2017). "This suggested that HOXB7 promoted the metastasis of hepatoma cells by activating PI3K/AKT/Slug to promote EMT." (PMID 28646927, 2017). "Collectively, our data suggested that HOXB7 accelerated hepatoma cell growth and metastasis by activating the AKT pathway to up-regulate c-Myc and Slug." (PMID 28646927, 2017). "Our results showed that the PI3K/AKT/c-Myc axis was modulated by HOXB7 to facilitate the acquisition of cancer stem-like properties in hepatoma cells." (PMID 28646927, 2017). "Our results revealed that HOXB7 facilitated hepatoma cell metastasis and up-regulated Slug expression." (PMID 28646927, 2017). "Meanwhile, the AKT pathway was activated by HOXB7 in hepatoma cells." (PMID 28646927, 2017). "The homeobox-containing gene HOXB7 plays an important role in the pathogenesis and progression of many cancers, yet its role in hepatocellular carcinoma (HCC) remains unclear." (PMID 28454092, 2017). "To determine whether HOXB7 regulates the stemness of hepatoma cells, we analysed the expression of cancer stem cell markers." (PMID 28646927, 2017). "Furthermore, we investigated the role of HOXB7 in several cancer-related processes, including proliferation, stemness, invasion and migration of hepatoma cells in vitro and vivo." (PMID 28646927, 2017). "The effect of HOXB7 on the invasion and migration abilities of hepatoma cells was examined." (PMID 28646927, 2017). "Overexpression of HOXB7 in hepatoma cells enhanced growth and metastasis in vitro and vivo." (PMID 28646927, 2017). "In addition, HOXB7 knockdown suppressed the cell proliferation, clone formation, sphere formation, invasion and migration of hepatoma cells in vitro; conversely, these biological abilities of hepatoma cells were enhanced by HOXB7 overexpression." (PMID 28646927, 2017). "Further investigation identified that HOXB7 not only promoted EMT, but also facilitated the acquisition of cancer stem-like properties in hepatoma cells." (PMID 28646927, 2017).
hepatocellular carcinoma (continued). "To assess the impact of HOXB7 on growth of hepatoma cells, we knocked down HOXB7 in SMMC-7721 cells using an shRNA specific to HOXB7 (HOXB7 shRNA#2) and overexpressed HOXB7 in HepG2 cells." (PMID 28646927, 2017). "Our results revealed that HOXB7 had a substantial impact on the EMT phenotypes of hepatoma cells, enhancing hepatoma cell motility and playing an important role in EMT." (PMID 28646927, 2017). "HOXB7 and RARA are schizophrenic genes with different gene expressions, modulated through the retinoid signaling pathway by the hepatocellular carcinoma over-expression gene PARP1." (PMID 24564241, 2013). "Furthermore, HOXB7 facilitated the EMT and stemness of hepatoma cells through the PI3K/AKT/Slug signaling pathway." (PMID 41040515, 2025). "Previous studies had shown that HOXB7 overexpression in hepatocellular carcinoma boosting c-Myc and Slug transportation and activated MAPK-AKT pathway to facilitate stem-like properties and EMT process in hepatoma cells, which finally malignant progression." (PMID 34303375, 2021). "Moreover, our results revealed that HOXB7 enhanced cancer stem-like properties and EMT in hepatoma cells." (PMID 28646927, 2017). "A recent study has reported that HOXB7 promoted the migration and invasion of hepatoma cells, but the related mechanism was not clear." (PMID 28646927, 2017).
lung adenocarcinoma (7 papers, 2014 to 2025). A carcinoma that arises from the lung and is characterized by the presence of malignant glandular epithelial cells. "We further verified their role in the development of lung adenocarcinoma by knocking down HOXB7 and HOXC6 in A549 and NCI-H1975 cells respectively." (PMID 39980564, 2025). "In lung adenocarcinoma cell lines, HOXB7 and HOXC6 were confirmed to markedly influence cell proliferation and migration, suggesting consideration as prognostic indicators." (PMID 39980564, 2025). "Increased expression of HOXB7 (within a 10‐gene prognostic signature) was shown to correlate with poor prognosis in lung adenocarcinoma." (PMID 32830458, 2021). "Again, HOXB7 is one of the genes composing the 10-gene signature, which we also recently showed to promote a stem cell-like phenotype in lung adenocarcinoma." (PMID 33333738, 2020). "All of the tumors showed positive immunostaining of HOXB7 protein, both in lung squamous cell carcinoma and lung adenocarcinoma tissues: 12 of 50 NSCLC cases (24.0%) showed weakly positive staining and 38 NSCLC cases (76%) showed strongly positive staining." (PMID 24853421, 2014). "Gene knockdowns were used to verify the effects of HOXB7 and HOXC6 on the proliferation and migration of lung adenocarcinoma (LUAD) cells." (PMID 39980564, 2025). "HOXB7 knockdown resulted in depression of migration and invasion with EMT alteration in lung adenocarcinoma." (PMID 28646927, 2017). "Additionally, GNLY, HOXB7, MRPL33, and PRDM16 were upregulated in bladder urothelial carcinoma, colon adenocarcinoma, lung adenocarcinoma, and rectum adenocarcinoma based on the results of eRic validation." (PMID 37534217, 2023).
pancreatic ductal adenocarcinoma (7 papers, 2013 to 2022). An infiltrating adenocarcinoma that arises from the epithelial cells of the pancreas. "Tissue microarray evaluation of 145 pancreatic ductal adenocarcinoma samples revealed that high expression of HOXB7 protein was associated with lymph node metastasis (P = .034), which resulted in poor prognostication in patients." (PMID 35945754, 2022). "Knocking out or overexpression of HOXB7 in pancreatic ductal adenocarcinoma cell lines leads to decreased or increased invasiveness, respectively." (PMID 35945754, 2022). "Up-regulation of HOXB7 in pancreatic ductal adenocarcinoma was correlated with poor prognosis of patients." (PMID 34303375, 2021). "Up-regulation of HOXB7 in pancreatic ductal adenocarcinoma was correlated with advanced stage of the disease." (PMID 28646927, 2017). "In previous studies, high levels of HOXB7 expression and low levels of miR-337 were detected in human pancreatic ductal adenocarcinoma tissues (PDAC)." (PMID 25183455, 2014). "HOXB7 mRNA expression was analyzed in 29 pancreatic ductal adenocarcinoma samples, 24 peritumoral tissue samples, 6 metastatic tissues samples, and 10 normal pancreatic tissue samples." (PMID 24088503, 2013). "Recently, increased expression of HOXB7 homeobox gene (HOXB7) in pancreatic ductal adenocarcinomas (PDAC) was shown to correlate with an invasive phenotype, lymph node metastasis and worse survival outcomes, but no influence on cell proliferation or viability was detected." (PMID 24088503, 2013). "Previous studies have shown that miR-337 is significantly down-regulated in pancreatic ductal adenocarcinoma (PDAC) and that its expression is negatively correlated to the expression of HOXB7." (PMID 25183455, 2014).
esophageal cancer (6 papers, 2019 to 2025). A primary or metastatic malignant neoplasm involving the esophagus. "Taken together, these findings suggested that esophageal cancer cells with HOXB7 silencing were more susceptible to X-ray irradiation and HOXB7 enhanced radioresistance of the cancer cells in vitro." (PMID 33330444, 2020). "The ensuing decreased transcription of HOXB7 inhibits proliferation and radio-resistance of esophageal cancer cell lines in vitro and in vivo." (PMID 34503076, 2021). "Having identified that MAGI2-AS3 regulated radio-resistance of esophageal cancer cells in vivo, we focused our attention on the effects of HOXB7 on esophageal cancer cell proliferation, apoptosis, and resistance to radiotherapy." (PMID 33330444, 2020). "Microarray-based analyses in the current study identified another differentially expressed lncRNA, MAGI2-AS3, along with a differentially expressed gene (DEG), homeobox protein Hox-B7 (HOXB7) in esophageal cancer." (PMID 33330444, 2020). "Initially, we detected high expression of HOXB7 from microarray-based gene expression profiling of esophageal cancer." (PMID 33330444, 2020). "RT-qPCR and Western blot analysis further verified that HOXB7 expression was much higher in esophageal cancer tissues relative to adjacent normal tissues (p < 0.05)." (PMID 33330444, 2020). "Taken together, our results reveal the potential role of MAGI2-AS3 over-expression in controlling esophageal cancer resistance to radiotherapy by down-regulating HOXB7, this providing a candidate biomarker for resistance to radiotherapy." (PMID 33330444, 2020). "The effect of MAGI2-AS3 and HOXB7 on esophageal cancer cell proliferation and apoptosis as well as tumorigenicity of radioresistant cells was examined by gain- and loss-of-function experiments." (PMID 33330444, 2020). "Reverse transcription quantitative polymerase chain reaction was employed to determine the expression of HOXB7 in human esophageal cancer cell lines (KYSE30, KYSE150, and KYSE450) and normal esophageal epithelial cell line (HEEC)." (PMID 33330444, 2020). "Results of IHC revealed that HOXB7 was primarily localized in the nucleus as brownish-yellow staining, with higher positive expression rate of HOXB7 protein in esophageal cancer tissues compared to adjacent normal tissues (p < 0.05)." (PMID 33330444, 2020). "Subsequently, the expression of HOXB7 was determined by RT-qPCR, Western blot analysis and IHC in esophageal cancer tissues and adjacent normal tissues." (PMID 33330444, 2020). "We further assessed the expression of HOXB7 in KYSE150 and KYSE150R cells to confirm the correlation between HOXB7 and resistance of esophageal cancer cells to radiotherapy." (PMID 33330444, 2020). "Cellular biological functions KYSE150R cells proved to be consistent with those in the KYSE150 cells, supporting the validation on the effects of MAGI2-AS3 restoration or HOXB7 silencing on radio-resistance of esophageal cancer cells." (PMID 33330444, 2020). "Our findings revealed that restoration of MAGI2-AS3 could function as a tumor suppressor by down-regulating its target gene HOXB7, thus attenuating radio-resistance in esophageal cancer cells." (PMID 33330444, 2020). "Finally, we investigated whether the role of MAGI2-AS3 in esophageal cancer cells was achieved by down-regulating HOXB7 in vivo." (PMID 33330444, 2020). "Furthermore, we show that MAGI2-AS3 and HOXB7 can serve as biomarkers for radio-resistance and that gene therapy through MAGI2-AS3 restoration or HOXB7 silencing may improve the treatment of esophageal cancer by overcoming radioresistance." (PMID 33330444, 2020). "Therefore, MAGI2-AS3 restoration could suppress radio-resistance of esophageal cancer cells in vivo by down-regulating HOXB7." (PMID 33330444, 2020). "In esophageal cancer, lncRNA MAGI2-AS3 can recruit the histone methyltransferase EZH2 to the HOXB7 promoter region to initiate H3K27me3 and repress HOXB7 expression, resulting in enhanced tumor radiosensitivity." (PMID 35600868, 2022).
esophageal cancer (continued). "In esophageal cancer, MAGI2-AS3 can down-regulate HOXB7 expression by recruiting the histone-lysine N-methyltransferase EZH2 (enhancer of zeste homolog 2) to promote the tri-methylation of lysine 27 on histone H3 in the HOXB7 promoter region." (PMID 34503076, 2021). "Our initial results demonstrated that esophageal cancer tissues and cell lines exhibited low expression of MAGI2-AS3 and high expression of HOXB7." (PMID 33330444, 2020). "The obtained evidence suggested that MAGI2-AS3 was negatively correlated with HOXB7, and MAGI2-AS3 localized in the nucleus was poorly-expressed in esophageal cancer, and down-regulated HOXB7 transcription in vitro." (PMID 33330444, 2020). "HOXB7 was highly-expressed, while MAGI2-AS3 was poorly-expressed in esophageal cancer tissues and cells." (PMID 33330444, 2020).
lymph node metastasis (6 papers, 2013 to 2020). "High FIGO stage also highly correlated with high HOXB7 expression, and lymph node metastasis was found to be associated with high HOXD12 and HOXD13 expression (P < 0.01)." (PMID 29137433, 2017). "Furthermore, in a cohort of 330 patient GC tumors, our study showed that HOXB7 immuno-positivity was observed in 59.1% of GC patients and was associated with increased tumor size, depth of invasion, lymph node metastasis, distant metastasis, and TNM stage." (PMID 27901487, 2017). "High HOXB7 protein expression in the tumor tissues was recently found to be correlated with lymph node metastasis and to be independent predictor of shorter overall survival." (PMID 24641834, 2014). "HOXB7 expression was positively correlated with the T stage, lymph node metastasis and TNM stage." (PMID 26076456, 2015). "Chi-square test showed that the expression levels of HOXB7 protein significantly correlated with TNM stage (P = 0.034), T stage (P = 0.036) and lymph node metastasis (P = 0.042)." (PMID 26076456, 2015). "The results showed that HOXB7 expression was positively correlated with the TNM stage (P = 0.034), T stage (P = 0.036), lymph node metastasis (P = 0.042)." (PMID 26076456, 2015). "Chi-square test showed that the expression levels of HOXB7 protein significantly correlated with TNM stage (P = 0.001), T stage (P = 0.000) and lymph node metastasis (P = 0.006)." (PMID 26076456, 2015). "A similar trend was noted in our results: HOXB7 expression in this cohort also showed a positive correlation with the TNM stage (P = 0.001), T stage (P = 0.000) and lymph node metastasis (P = 0.006)." (PMID 26076456, 2015). "The HOXB7 positive staining rate in the patients with lymph node metastasis was greater (73.8%, or 158/214) than in patients without lymph node metastasis (31.9%, or 37/116, P<0.05)." (PMID 27901487, 2017). "Recently HOXB7 status was investigated in a large cohort of PDAC, the authors observed overexpression of HOXB7 and its correlation with invasive phenotype, lymph node metastasis and worse survival outcomes, but no influence on cell proliferation or viability was detected." (PMID 24088503, 2013).
multiple myeloma (6 papers, 2012 to 2025). "More evidences were observed in multiple myeloma expressing HOXB7 to regulate myeloma pro-angiogenic properties." (PMID 31013831, 2019). "It has recently been demonstrated that the forced expression of HOXB7 in multiple myeloma induces the up-regulation of VEGFA, FGF2, MMP2 and PDGFA, and the down-regulation of thrombospondin 2, a profile largely shared by RC." (PMID 25115389, 2014). "HOXB7 is possibly important in the angiogenic properties of myelomas but the near ubiquitous expression of HOXB7 in all endothelial lines (and the relative absence in other cell lines) in our microarray studies suggests a more fundamental role in endothelial biology." (PMID 24651450, 2014).
oral cancer (6 papers, 2015 to 2025). "Evidence shows the overexpression of HOXB7 promotes cell survival and induces chemo‐radiotherapy resistance in oral cancer." (PMID 35810383, 2022). "It was found that down-regulated miR-376c-3p suppresses the cancer phenotype by targeting homeobox B7 (HOXB7) in oral cancer tissue as well as in cell lines." (PMID 29482431, 2018). "In contrast, HOXA7, HOXA10, HOXB7, HOXC6, HOXC10, HOXD10, and HOXD11 were consistently upregulated in potentially malignant oral lesions as they advanced to oral cancer." (PMID 41477365, 2025). "HOXA7, HOXA10, HOXB7, HOXC6, HOXC10, HOXD10, HOXD11 showed consistent upregulation in the potentially malignant oral lesions through their progression to oral cancer, which indicated the posterior prevalence of the HOX genes during cancer progression." (PMID 35710803, 2022).
lung carcinoma (5 papers, 2013 to 2022). "In lung cancer, HOXB7 overexpression increases several iPSC markers and sustains the stemness of stem cell subpopulation by modulation of LIN28B." (PMID 34303375, 2021). "Quantitative real‐time RT‐PCR (qRT‐PCR) analyses of total RNA isolates generated from directly ex vivo isolated normal lung or lung carcinoma tissues revealed a significant upregulation of HOXB7 and HOXC6, as well as HOXC8 mRNA by tendency expression in the NSCLC tissues." (PMID 32830458, 2021). "Moreover, HOXB2, HOXB4 and HOXB7 together showed the key function in lung cancers." (PMID 23630576, 2013).
non-small cell lung carcinoma (5 papers, 2014 to 2021). A group of at least three distinct histological types of lung cancer, including non-small cell squamous cell carcinoma, adenocarcinoma, and large cell carcinoma. "But in another study, knockdown of TUG1 promoted tumor cell proliferation in non-small cell lung carcinoma via regulation of the expression of homeobox B7 (HOXB7)." (PMID 26078353, 2015). "Our previous study showed that TUG1 could affect cell proliferation through epigenetically regulating HOXB7 in human non-small cell lung cancer." (PMID 26913601, 2016). "However, TUG1 has been shown to act as a tumor suppressor in non-small cell lung cancer, where TUG1 knockdown promoted tumor cell proliferation through epigenetic regulation of HOXB7 expression." (PMID 29371936, 2017).
cyst (4 papers, 2017 to 2024). A sac-like closed membranous structure that may be empty or contain fluid or amorphous material. "Since the failure to observe cyst formation in our Arf4flox/CagCreER animals was unexpected, we used HoxB7-Cre as a second method to delete Arf4." (PMID 28410364, 2017). "In the Pkd1f/f:HoxB7-Cre mice, as expected, miR-182-5p was strongly expressed in the cyst-lining epithelial cells." (PMID 29074972, 2017). "Expression of candidate DEmiR targets associated with the actin cytoskeleton were gradually changed along with cyst progression in Pkd1f/f:HoxB7-cre mice." (PMID 29074972, 2017). "Several dilated tubules were observed in both kidneys from Pkd1f/f:HoxB7-cre mice at P1 and occasional cyst formation was observed starting at P3 in these mice." (PMID 29074972, 2017). "Interestingly, miR-182-5p-expressing cells were observed in the cuboidal epithelial lining cells of the cyst in Pkd1f/f:HoxB7-Cre mice at P7." (PMID 29074972, 2017).